IDO2 (indoleamine 2,3-dioxygenase 2)
Diseases named in the same sentence as IDO2 in open-access papers (continued):
Sharing a sentence is not in itself a finding about the gene and the disease.
psoriasis (4 papers, 2020 to 2023). An autoimmune condition characterized by red, well-delineated plaques with silvery scales that are usually on the extensor surfaces and scalp. "In contrast with these studies, in a model of psoriasis-like inflammation, the manifestations of the disease were significantly worse in the IDO2 KO mice." (PMID 33968089, 2021). "The mRNA expression levels of TNF-α, IL-23p19, and IL-17A, key cytokines involved in the development of psoriasis, were also increased in the IDO2 KO mice." (PMID 32752186, 2020). "In this study, to elucidate the role of IDO2 in psoriasis, we assessed IMQ-induced psoriasis-like dermatitis in IDO2 knockout (KO) mice." (PMID 32752186, 2020). "The pathogenesis of psoriasis may involve the dysfunction of indoleamine 2,3-dioxygenase 2 or of UBA domain containing 1-mediated regulation of CARD14/CARMA2sh." (PMID 33804147, 2021). "Our results showed that IDO2 deletion in mice exacerbated IMQ-induced psoriasis-like dermatitis." (PMID 32752186, 2020). "To elucidate whether IMQ-induced psoriasis-like inflammation is related to IDO2, we next assessed the effect of IMQ on the skin of IDO2 KO and WT mice." (PMID 32752186, 2020). "Instead, the role of IDO2 in psoriasis had remained unclear until now." (PMID 32752186, 2020). "However, the deterioration of psoriasis-like skin lesions on the ear after 7 days of IMQ treatment was more pronounced in IDO2 KO than in WT mice." (PMID 32752186, 2020). "However, 48 h and 7 days after IMQ treatment, the mRNA levels of most key cytokines involved in psoriasis development were higher in IDO2 KO than in WT mice." (PMID 32752186, 2020). "Therefore, the results obtained in the murine model of psoriasis add more complexity than reinforcing the hypothesis of a proinflammatory role of IDO2." (PMID 33968089, 2021). "Our data show that IDO2 might suppress IMQ-induced psoriasis-like skin inflammation." (PMID 32752186, 2020). "However, the role of IDO2 in the pathogenesis of psoriasis remains unclear." (PMID 32752186, 2020). "In this study, to elucidate the role of IDO2 in psoriasis, we assessed imiquimod (IMQ)-induced psoriasis-like dermatitis in IDO2 knockout (KO) mice." (PMID 32752186, 2020). "In addition, IDO2 may provide an effective means of treating psoriasis." (PMID 32752186, 2020). "Moreover, the epidermis of the ears of IDO2 KO mice treated with IMQ was significantly thicker than that of WT mice, indicating that IMQ-induced psoriasis-like skin inflammation was significantly exacerbated in IDO2 KO mice." (PMID 32752186, 2020). "Based on our data, we propose that IDO2 might decrease IL-17 expression, leading to the suppression of skin inflammation in IMQ-induced psoriasis-like dermatitis." (PMID 32752186, 2020). "Our results suggest that IDO2 might modulate the IL-17 signaling pathway, leading to decreased IL-17 expression and suppressing the skin inflammation in IMQ-induced psoriasis-like dermatitis." (PMID 32752186, 2020). "Our results also show that, in the epidermis of patients with psoriasis and WT mice treated with IMQ, IDO2 was expressed but IDO1 was not." (PMID 32752186, 2020).
rheumatoid arthritis (4 papers, 2014 to 2024). A chronic, systemic autoimmune disorder characterized by inflammation in the synovial membranes and articular surfaces. "The three rate-limiting enzymes of the Trp-Kyn pathway are IDO1, IDO2, and TDO2, with IDO1 promoting inflammation in rheumatoid arthritis (RA)." (PMID 38724970, 2024).
gastric cancer (3 papers, 2021 to 2025). A primary or metastatic malignant neoplasm involving the stomach. "In this study, we found that EBV+ gastric cancer, HPV+ cervical and head-neck squamous cell cancer, and HCV+ liver cancer (but not HBV+ liver cancer) showed over-expression of IDO-1, but only EBV+ gastric cancer and HPV+ head and neck squamous cell cancer showed over-expression of IDO-2." (PMID 34367262, 2021).
liver cancer (3 papers, 2021 to 2024). An epithelial or non-epithelial malignant neoplasm that arises from the liver. "IDO1 was elevated in 50% of liver cancer samples while IDO2, TDO2, and AFMID were predominantly downregulated." (PMID 38769298, 2024).
schizophrenia (3 papers, 2016 to 2023). A major psychotic disorder characterized by abnormalities in the perception or expression of reality. "Here we examined the relative expression of DRD1, DRD2 and IDO1 and IDO2 genes transcription in MK-801 model schizophrenia group and T. gondii infected rat brain and subsequent neurotransmitter changes." (PMID 36950587, 2023).
Sepsis (3 papers, 2018 to 2024). Sepsis is defined as life-threatening organ dysfunction caused by a dysregulated host response to infection. "Further study is needed to clarify the relationship between the pathophysiology of sepsis and Trp degradation enzymes, but our data suggested that Ido2 has an important function in LPS induced endotoxin models." (PMID 30374077, 2018). "In a noncardiac pediatric sepsis population, a high IDO2 up to 12 hours after hospital admission was associated with major adverse events and worse outcomes." (PMID 39780782, 2024). "The relationship between the pathophysiology of sepsis and Trp degradation enzymes, such as tryptophan 2,3-dioxygenase 2 (TDO2), Ido1 and Ido2, are reported." (PMID 30374077, 2018).
viral infection (3 papers, 2016 to 2021). "Ido1, Ido2, and Tdo2 messenger RNA (mRNA) expression are induced within the brain and peripheral tissues by LPS and bacterial infection, pI:C and viral infection, and systemic and CNS administration of pro-inflammatory cytokines." (PMID 27142940, 2016). "Together, these data suggest that the observed systemic increase of kynurenine during homeostasis and upon viral infection of Tdo2-deficient animals is unlikely to be due to altered hepatocyte-intrinsic activity of IDO1 or IDO2." (PMID 33045014, 2020). "The presence of a significant LPS and pI:C effect on Ido2 expression may relate to an undiscovered role for Ido2 during bacterial and viral infections within the brain." (PMID 27142940, 2016). "This suggests that exogenous viral infection in tumor (e.g., EBV, HPV, and HCV) is associated with the over-expression of IDO-1 and sometimes IDO-2 but not TDO-2." (PMID 34367262, 2021). "Thus, Ido2 expression is responsive to peripheral immune-cell-derived IFNγ (resident cells in the brain do not produce IFNγ) and bacterial or viral infections (via LPS or dsRNA) but relatively unaffected by stress hormones." (PMID 27142940, 2016).
African trypanosomiasis (2 papers, 2019 to 2024). "More so, three unique Muturu candidate genes, namely FAS, IDO2, and PLCB1, are part of the candidate African trypanosomiasis KEGG pathway (BTA05143) revealed following functional annotation terms by DAVID bioinformatic tool." (PMID 31231417, 2019).
aspergillosis (2 papers, 2019 to 2021). Aspergillosis is an infection, growth, or allergic response caused by the Aspergillus fungus. "Whatever the approach, these results are expected to pave the way for the pharmacological targeting of IDO2 in aspergillosis in high-risk patients, as recently explored in autoimmune arthritis with the development of an IDO2-targeted therapeutic antibody." (PMID 31134053, 2019). "In support of this hypothesis, a recent study revealed that, in two different cohorts of patients with aspergillosis, specific and different patterns of IDO2 single nucleotide polymorphisms (SNPs) can be observed." (PMID 33968089, 2021). "However, the same two IDO2 SNPs associated with aspergillosis in HSCT recipients." (PMID 31134053, 2019). "With regard to IDO2, our study showed that the two IDO2 SNPs, leading to truncated or catalytically impaired IDO2 protein, do not associate with an increased risk for aspergillosis in CF patients." (PMID 31134053, 2019).
cardiac arrest (2 papers, 2022 to 2024). Cessation of breathing and/or cardiac function. "In prior studies, an elevated IDO2 index predicted cardiac arrest 120 minutes prior to the arrest in neonates after cardiopulmonary bypass surgery, and predicted failure to wean vasoactive medications in postoperative pediatric cardiac surgery patients." (PMID 39780782, 2024). "Previous studies in pediatric ICUs have demonstrated that accumulated time with high IDO2 can predict cardiac arrest, failure to wean off vasoactive medications, and adverse events in critically ill children." (PMID 39780782, 2024). "Additionally, a low IDO2 index may rule out a risk for cardiac arrest in critically ill pediatric patients who are classified as high-risk for cardiac arrest by standard clinical evaluation." (PMID 39780782, 2024).
Chlamydia infection (2 papers, 2019 to 2021). "The lung IDO2 mRNA was clearly induced by Chlamydia infection, but its RNA-seq read numbers were significantly lower than IDO1 reads." (PMID 31249813, 2019). "Next, we explored whether the expression of IFN-γ and IFN-γ induced genes was altered in FP- and BUD-treated lung tissues, including the typical, inducible defence genes against Chlamydia infection, such as indoleamine 2,3-dioxygenase 1 (IDO1), IDO2, MIG/CXCL9, IP-10/CXCL10 and I-TAC/CXCL11." (PMID 33799333, 2021).
colon cancer (2 papers, 2021 to 2022). "As opposed to the low-risk colon cancer patients, the high-risk cases showed higher expressions of CTLA-4 (p < 0.001), PD-1 (p < 0.01), PD-L1 (p < 0.001), IDO1 (p < 0.05), IDO2 (p < 0.05), HAVCR2 (p < 0.001), and LAG3 (p < 0.05)." (PMID 36280825, 2022).
Crohn disease (2 papers, 2014 to 2024). A gastrointestinal disorder characterized by chronic inflammation involving all layers of the intestinal wall, noncaseating granulomas affecting the intestinal wall and regional lymph nodes, and transmural fibrosis. "IDO2 minor allele variants were common and one of them, rs45003083, associated with reduced risk of Crohn's disease (p = 0.025)." (PMID 25541686, 2014). "However, although IDO2 minor allele variants are common and one of them, rs45003083, is associated with reduced risk of Crohn’s disease, none of the IDO2 SNPs is associated with a particular Crohn’s disease clinical phenotype." (PMID 39594642, 2024). "No IDO2 SNPs associated with a particular Crohn's disease clinical phenotype." (PMID 25541686, 2014).
endometrial cancer (2 papers, 2020 to 2021). Primary or metastatic malignant neoplasm involving the endometrium (mucous membrane that lines the endometrial cavity). "ERV3-2 expression was correlated with all three genes in ER− HER2− and HER2+ breast, colon, and endometrial cancers; and IDO-1 and IDO-2 (but not TDO-2) in ER+ HER2− breast, gastric, lung, prostate, cervical, and head-neck squamous cell cancers." (PMID 34367262, 2021).
Lewis lung carcinoma (2 papers, 2023). "Studies by Yamasuge and colleagues demonstrated that Ido2 knockout (KO) tumors had higher intratumor Trp and reduced Kyn levels compared to wild-type Ido2 tumors in a Lewis lung carcinoma mouse model, indicating Ido2 Trp catalytic activity." (PMID 37876966, 2023).
lupus (2 papers, 2019). "To establish if IDO was dysregulated in lupus-prone B6.Nba2 mice, we tested basal levels of IDO1 and IDO2 in spleens from unmanipulated female B6.Nba2 strains and control age- and sex-matched B6 mice." (PMID 31555267, 2019).
lymph node metastasis (2 papers, 2006 to 2022). "Given the significant correlation between IDO2 expression and the status of lymph node metastasis, we further examined the expression of IDO2 in the corresponding lymph nodes." (PMID 36319978, 2022). "Of all the clinicopathological characteristics, the expression level of IDO2 had the most significant effect on lymph node metastasis." (PMID 36319978, 2022). "In patients with lymph node metastases, the proportion of IDO2-high patients was much higher than its counterparts (63% vs. 37%)." (PMID 36319978, 2022). "MTC patients with lymph node metastasis tend to have higher levels of IDO2 expression (P < 0.001)." (PMID 36319978, 2022). "Since female patients were more likely to be manifested as a IDO2-low status, this finding further validated the view that MTC patients with lymph node metastasis tend to have higher levels of IDO2 expression." (PMID 36319978, 2022). "In the IDO2-low group, thirty-three (66.4%) patients presented as pN0 stage, whereas only fourteen (18.2%) patients in the IDO2-high group had no lymph node metastasis." (PMID 36319978, 2022). "The high IDO expression (IDO2+ or 3+) in tumour cells was found in 37 (46.3%) of the 80 cases, and was positively correlated with surgical stage, myometrial invasion, lymph-vascular space involvement, and lymph node metastasis, but not with the histological grade." (PMID 17117179, 2006).
medullary thyroid carcinoma (2 papers, 2022 to 2024). "The linkage between IDO2 expression and cancer progression is still unclear, particularly in medullary thyroid carcinoma (MTC)." (PMID 36319978, 2022). "Immunohistochemistry analyses demonstrated a significant presence of IDO2 in NSCLC, medullary thyroid carcinoma, B and T cell lymphomas, ovarian cell carcinoma, and glioblastoma." (PMID 39594642, 2024).
ovarian carcinoma (2 papers, 2020 to 2024). A malignant neoplasm originating from the surface ovarian epithelium. "Note, based on Cancer Dependency Map (DepMap) and TCGA, ovarian cancer cells do not express IDO2." (PMID 38451784, 2024).
renal cell carcinoma (2 papers, 2016 to 2024). "Human primary tumors, such as gastric, colon and renal cell carcinomas, constitutively express IDO2 mRNA, whereas its expression in cancer cell lines has to be induced by IFN-γ." (PMID 27058624, 2016).
squamous cell carcinoma (2 papers, 2020 to 2021). A carcinoma arising from squamous epithelial cells. "IDO2 high expression is strictly related to high PD-L1 level among squamous cell carcinomas group (p = 0.012), to either intratumoral or mixed localization of TILs (p < 0.001) and to adenocarcinoma histotype (p < 0.001)." (PMID 32536910, 2020). "From a biological point of view, our results show that PD-1, PD-L2 and IDO-2 gene expression levels were significantly higher in patients with squamous cell carcinoma and PD-1, PD-L1 and IDO-2 gene expression levels were significantly higher in patients with higher TNM stage." (PMID 33671892, 2021). "Interestingly, we found a high co-expression of both PD-L1 and IDO2 in the squamous cell carcinomas subgroup, further evidence that IDO2 expression occurs in cells displaying tolerance markers." (PMID 32536910, 2020). "In addition, a high IDO2 level was more frequently present in adenocarcinomas than in the squamous cell carcinoma subgroup, a finding that corroborates the strict relationship between this molecule and the specific microenvironment of this NSCLC histotype." (PMID 32536910, 2020). "Interestingly, a high IDO2 expression correlated with high PD-L1 among the squamous cell carcinomas group (p = 0.012; OR = 6.2)." (PMID 32536910, 2020).
abortion (1 paper, 2021). the ending of pregnancy by removing a fetus or embryo before it can survive outside the uterus. "Simultaneously, dysfunction in IDO2 could lead to recurrent spontaneous abortion, preeclampsia, preterm labor, and fetal growth restriction." (PMID 33613628, 2021).
acute myeloid leukemia (1 paper, 2021). Acute myeloid leukemia (AML) is a group of neoplasms arising from precursor cells committed to the myeloid cell-line differentiation. "IDO-2 and TDO-2 expression showed a similar pattern, with high expression in diffuse large B-cell lymphoma and low expression in acute myeloid leukemia." (PMID 34367262, 2021).
breast tumors (1 paper, 2018). "Interestingly, IDO1 levels, but not IDO2 levels (not expressed), were significantly elevated in high AHR-expressing breast tumors compared to low AHR-expressing breast tumors in both ERα subpopulations." (PMID 29320557, 2018).
cholangiocarcinoma (1 paper, 2023). A carcinoma that arises from the intrahepatic biliary tree (intrahepatic cholangiocarcinoma) or from the junction, or adjacent to the junction, of the right and left hepatic ducts (hilar cholangiocarcinoma). "In general, IDO2 mRNA expression increased in cancer types relative to normal samples, although several exceptions were observed, including cholangiocarcinoma (CHOL), liver hepatocellular carcinoma (LIHC), and thyroid carcinoma (THCA)." (PMID 37408267, 2023).
chronic fatigue syndrome (1 paper, 2023). "Symptoms of PASC are related to symptoms of patients with chronic fatigue syndrome, but although a link with IDO2 expression was proposed, be it as an enzymatically inactive enzyme, there is no proof of IDO2 expression in this heterogeneous patient group." (PMID 37506544, 2023).
Cluster headache (1 paper, 2020). A type of headache characterized by repeated attacks of unilateral pain lasting 15 to 180 minutes and associated with local autonomic signs. "The IDO-1, IDO-2, and KMO enzymes and the kynurenine metabolite have been shown to be involved in the pathogenesis of neuropathic pain and other painful conditions (migraine, cluster headache, etc.)as well as depressive behavior." (PMID 32842609, 2020).
Dengue (1 paper, 2020). "As Dengue patients seem to present with lower tryptophan and higher kynurenine concentrations in the serum, we decided to include IDO1 and IDO2 genes in the analysis." (PMID 32117223, 2020).
dermatitis (1 paper, 2020). An inflammatory process affecting the skin. "To investigate whether the mechanism that regulates IMQ-induced dermatitis by IDO2 is associated with tryptophan metabolites, we measured the concentration of tryptophan metabolites in the ears of treated mice using HPLC." (PMID 32752186, 2020). "Skin inflammation, evaluated by scoring erythema, scaling, and ear thickness, was significantly worse in the IDO2 KO mice than in the wild-type (WT) mice." (PMID 32752186, 2020). "IMQ treatment induced a psoriasiform skin inflammation in both WT and IDO2 KO mice." (PMID 32752186, 2020). "The mechanism by which IDO2 controls IMQ-induced dermatitis remains unclear." (PMID 32752186, 2020). "Therefore, the mechanism by which IDO2 regulates IMQ-induced dermatitis might not be associated with tryptophan metabolites, and our results on the metabolites might just reflect the consequences of inflammation caused by IMQ treatment." (PMID 32752186, 2020). "By contrast, because IDO2 is strongly expressed in the epidermis, it might influence IMQ-induced dermatitis." (PMID 32752186, 2020). "Therefore, IDO2 might modulate STAT3 signaling, leading to decreased IL-17 expression and suppressing IMQ-induced dermatitis." (PMID 32752186, 2020).
end-stage renal disease (1 paper, 2019). "In a nephrotoxic serum nephritis mouse model, IDO enzymatic inhibition using 1-MT (-d or -l isomer) exacerbated proteinuria and end-stage renal disease signifying a protective role for IDO, although whether this can be accredited to IDO1 or IDO2 was not determined." (PMID 31555267, 2019).
Erythema (1 paper, 2020). Redness of the skin, caused by hyperemia of the capillaries in the lower layers of the skin. "Individual scores for erythema, scaling, and ear thickness were significantly increased in IDO2 KO mice." (PMID 32752186, 2020).
gastric tumors (1 paper, 2022). "Interestingly, IDO1 levels, but not IDO2 levels (not expressed), were significantly elevated in high AhR expressing gastric tumors." (PMID 35203450, 2022).
HIV-1 infection (1 paper, 2013). The type species of lentivirus and the etiologic agent of acquired immunodeficiency syndrome (AIDS). "Unlike the changes in IDO-1 expression, IDO-2 mRNA expression was not different between study groups, thus highlighting the pivotal immunosuppressive role of IDO-1 in HIV-1 infection." (PMID 24147117, 2013).